AGO2 (argonaute RISC catalytic component 2)
Diseases named in the same sentence as AGO2 in open-access papers (continued):
Sharing a sentence is not in itself a finding about the gene and the disease.
breast carcinoma (continued). "In the breast cancer TMAs, 4 distinct staining intensities were observed (Negative, Weak, Moderate, Strong), with 64.2% of samples stained weak or negatively for Ago2 protein." (PMID 31324173, 2019). "Further work is needed to characterise the molecular mechanisms that regulate Ago2 localisation and stability in breast cancer cells." (PMID 31324173, 2019). "Here we investigated the value of evaluating Ago2 levels (protein and transcript) as markers in breast cancer." (PMID 31324173, 2019). "The staining in the representative cell lines correlated with the protein patterns seen in the TMA, suggesting that the cell lines are a good model to further explore the role of Ago2 in breast cancer." (PMID 31324173, 2019). "In this study, we investigated the contribution of Ago2, the only human Ago protein endowed with nuclease activity, to the function of tumor-suppressor miR-145-5p in breast cancer (BC)." (PMID 30622242, 2019). "This argues against Ago2 downregulation as a constant mechanism controlling breast cancer progression clinically." (PMID 31506588, 2019). "Using the cBioPortal we investigated copy number variations (CNVs) of the Ago2 gene in breast cancer." (PMID 31324173, 2019). "In agreement, the transfection of miR-145-5p inhibitor oligonucleotide in Hs578T breast cancer cells, expressing high level of miR-145-5p, led to a decrease of Ago2 protein level compared to control inhibitor." (PMID 30622242, 2019). "Aiming to investigate the contribution of Ago2 to miR-145-5p function in breast cancer, we first evaluated their expression in BC tissues." (PMID 30622242, 2019). "To investigate the functional output of miR-145-5p-Ago2 axis, we decided to evaluate its impact on cell migration, a function controlled by miR-145-5p in breast cancer cells." (PMID 30622242, 2019). "As observed in the breast cancer cell lines, the Ago2 staining pattern observed in the TMA was mainly cytoplasmic (of varying intensities), with nuclear staining observed within the strong staining pattern (Strong)." (PMID 31324173, 2019). "In breast cancer we found high levels of Ago2 gene amplification (almost 18%) and that high Ago2 expression significantly correlated with an increased chance of relapse." (PMID 31324173, 2019). "Together with the previously published data, our work supports further investigation of the role of Ago2, both miRNA dependent and independent, as a relevant factor influencing breast cancer (initiation, maintenance or progression)." (PMID 31324173, 2019). "An independent breast cancer gene expression database was then used to investigate if the correlations observed in the TMA matched changes observed in Ago2 gene expression." (PMID 31324173, 2019). "We demonstrate that quantification of Ago2 protein levels in breast tumour samples correlates with tumour size, ER and PR status and that this can be used to improve the ability to predict breast cancer subtype (by 20%)." (PMID 31324173, 2019). "The aim of this work was to investigate and quantify Ago2 dysregulation (mRNA and protein) in breast cancer." (PMID 31324173, 2019). "We investigated the expression of Ago2 mRNA and protein in breast cancer and found that there were distinct patterns of Ago2 protein expression, however a larger cohort will be needed to confirm if these patterns are significant." (PMID 31324173, 2019). "The results from MCF7 and MDA-MB-231 cells argues for Ago2 downregulation as a mechanism to lower the effectiveness of the miRNA machinery in aggressive breast cancer cells resulting in increased STIM1 expression to support cell migration." (PMID 31506588, 2019). "Further molecular work investigating the cellular consequences, of both up and down regulation of Ago2 are needed to clarify its role in breast cancer." (PMID 31324173, 2019).
breast carcinoma (continued). "To test this, we first selected a few genes among the most significantly downregulated by miR-145-5p in presence of Ago2, we validated their modulation and we evaluated their predictive power using various breast cancer cohorts." (PMID 30622242, 2019). "Using independent databases, Ago2 mRNA expression and gene alterations in breast cancer were investigated." (PMID 31324173, 2019). "Quantification of Ago2 improves the stratification of breast cancer and suggests a differential role for Ago2 in breast cancer subtypes, based on levels and cellular localisation." (PMID 31324173, 2019). "Consistent with this conclusion the levels of Ago2 expression increased with the severity of the breast cancer subtype." (PMID 31506588, 2019). "Investigating Ago2 mRNA expression and DFS, we find evidence of a difference in DFS comparing Ago2 expression Low and High, when considering all breast cancers (p = 0.0012, n = 1764)." (PMID 31324173, 2019). "Investigating Ago2 protein intensity and localisation using IHC in breast cancer cell lines, overall all breast cancer cell lines displayed stronger Ago2 staining, compared to MCF-10A (with very weak staining)." (PMID 31324173, 2019). "Further investigation of the mechanisms affecting Ago2 dysregulation will reveal insights into the molecular differences underpinning breast cancer subtypes." (PMID 31324173, 2019). "Overall, using a larger cohort (through the online repositories) we found that high Ago2 mRNA expression correlates with a poor relapse free survival in breast cancer." (PMID 31324173, 2019). "A number of studies have shown Ago2 modulation also in breast carcinoma, providing contradictory results." (PMID 30622242, 2019). "Ago2 protein was stained in breast cancer cell lines and tissue microarrays (TMAs), with intensity and localization assessed." (PMID 31324173, 2019). "For example, miR-423-5p recruits AGO2 to repress the transcription of progesterone receptor via inducing DNA methylation and H3K9me2 enrichment in breast cancer cells." (PMID 28827574, 2017). "The role of AGO2 in the composition of the miRNA machinery and the regulation of miRNA target stability and translation is well documented, among others, in breast cancer (BC) cells." (PMID 29017520, 2017). "In this study we further evaluate the expression of AGO2 across breast cancer tumor samples with different degrees of receptor status (ERα, PGR, and HER2) and tumor molecular subtype." (PMID 29657266, 2016). "Among breast tumor types, increased AGO2 expression in ERα− breast cancer cell lines and tumor samples has been observed." (PMID 29657266, 2016). "A positive correlation between AGO2 expression levels and the ERα− phenotype in breast cancer cell lines and tumor samples has been previously reported with AGO2 expression being regulated by EGFR/MAPK signaling." (PMID 29657266, 2016). "In this study, we show that a high expression of Argonaute 2 (AGO2), a translation regulatory protein and mediator of miRNA function, correlates with the luminal B breast cancer subtype." (PMID 29657266, 2016). "To identify possible mechanisms for the enhanced E2 response observed in vivo, we analyzed TCGA ERα positive breast cancer samples for a correlation of expression between AGO2 and ERα transcript gene expression." (PMID 29657266, 2016). "Furthermore, the co-reduction in oncogenic miRNA levels (miR-9 and miR-221) was a result of the down-modulation in AGO2 in breast cancer cells in vitro." (PMID 36613808, 2022). "Our hypothesis of the mechanism underlying the effects of UA on the decreased ability to invade and migrate casually to link miR-9 and miR-221 was due to the inhibition of AGO2 in breast cancer cells." (PMID 36613808, 2022). "Furthermore, a significant number of published data documents the potential of AGO2 as a biomarker in breast cancer." (PMID 33668654, 2021).
breast carcinoma (continued). "Moreover, as anticipated by the radioimmunoprecipitation experiment, LINC02568 and miR-874-3p enrichment was verified in Ago2 precipitates, which implied their binding interactions in breast cancer cells." (PMID 37303942, 2021). "For instance, the involvement of AGO2 in transcriptional activation was described in breast cancer cells, in which AGO2 was found to promote cell growth by inducing mRNA synthesis of the progesterone receptor (PR) by binding to the promoter region of the PR gene." (PMID 33668654, 2021). "The results suggest that splicing may change the role of genes.AGO2 is a Protein Coding gene, which have effect on cervical cancer, breast cancer and other tumors." (PMID 34526089, 2021). "Furthermore, ERβ has recently been shown to indirectly interact with Argonaute 2 (Ago2) in breast cancer cell lines, suggesting a role for ERβ in RISC loading." (PMID 34564315, 2021). "Furthermore, PPP1R14B-AS1, miR-134-3p and LASP1 were abundant in products immunoprecipitated by anti-Ago2 antibody in breast cancer cells." (PMID 37303940, 2021). "Here, we identified that FGF14-AS2 was mainly located in the cytoplasm of breast cancer cells and could interact with AGO2, which suggests that FGF14-AS2 may function as an endogenous miRNA sponge." (PMID 33083023, 2020). "In addition, LINC00665 and miR-379-5p were significantly enriched in AGO-containing microribonucleoprotein complexes by RNA immunoprecipitation (RIP) assay, suggesting that both LINC00665 and miR-379-5p bind directly to AGO2 in breast cancer cells." (PMID 31907362, 2020). "A. Ago2 gene amplification in indicated Breast cancer databases." (PMID 31324173, 2019). "Importantly, knowledge of Ago2 expression improves predictions of breast cancer subtype by 20%, ER status by 15.7% and PR status by 17.5%." (PMID 31324173, 2019). "According to the Human Protein Atlas Ago2 localises predominantly to the nucleus and cell-cell junctions in 3 distinct cancer types, with breast cancer localisation unknown." (PMID 31324173, 2019). "The apparent disconnect between transcript and protein levels suggests that the turnover/stability of Ago2 protein is tightly and differentially regulated in breast cancer subtypes, as has previously been demonstrated in ER positive cells, which can in turn influence growth rates." (PMID 31324173, 2019). "Moreover, we show that miR-145-5p specifically induces post-transcriptionally Ago2 protein expression in both breast and non-breast carcinoma cell lines." (PMID 30622242, 2019). "On the basis of the downregulation observed for both miR-145-5p and Ago2 in BC, we moved to breast cancer cell lines, to evaluate whether modulation of miR-145-5p levels had any effect on Ago2 expression." (PMID 30622242, 2019). "Our findings suggest that Ago2 downregulation in breast cancer might strongly influence the activity of miRNAs and highlight the importance of evaluating Ago proteins levels when studying miRNAs activity in cancer." (PMID 30622242, 2019). "In addition to profiling the total levels of Ago2, localisation of Ago2 protein in the breast cancer cell lines was explored." (PMID 31324173, 2019). "Interestingly, high levels of Ago2 gene amplification (10–27%) were observed in breast cancer across multiple patient datasets." (PMID 31324173, 2019). "Our study shows that both miR-145-5p and Ago2 protein are downregulated in breast cancer." (PMID 30622242, 2019). "We wondered whether Ago2 activity influenced the tumor suppressor/oncogenic function of miR-145-5p in breast cancer cells." (PMID 30622242, 2019). "In this study, we demonstrated a moderate elevation in miR-22 expression in the 182R-6 fulvestrant-resistant breast cancer line we used as a model system, and this elevation was positively correlated with the expression of the miRNA biogenesis enzymes AGO2 and Dicer." (PMID 30057418, 2018).
breast carcinoma (continued). "The fulvestrant-resistant 182R-6 breast cancer cell line showed a moderate upregulation of miR-22, which could be attributed to the miRNA biogenesis enzyme AGO2 and Dicer." (PMID 30057418, 2018). "The high expression of AGO2 was reported to correlate with the luminal B subtype of breast cancer." (PMID 30545127, 2018). "Resveratrol has also been found to decrease the portion of breast cancer stem-like cells by increasing Argonaute2 (Ago2, a component of RNA-inducing silencing complex, RISC) expression through enhancing promoter activity and prolonging half lives of mRNA and protein." (PMID 28052018, 2017). "In breast cancer cell lines, it was shown that the overexpression of AGO2 could induce the transformed phenotype." (PMID 22639842, 2012). "Furthermore, AGO2 has been shown to decrease PTEN expression in HCC angiogenesis, whereas PTEN caused apoptotic death by repression of the c-Myc transcript in human breast cancer cells." (PMID 36613808, 2022). "Therefore, the expression levels of Ago2 mRNA in breast cancer were investigated." (PMID 31324173, 2019). "However analysis of clinical data argue against Ago2-dependent STIM1 upregulation as a consistent mechanism supporting breast cancer progression, because even in the most aggressive basal-like subtype there is no negative correlation between Ago2 and STIM1 expression." (PMID 31506588, 2019). "Breast cancer cell-derived exosomes contain components of the RNA-induced silencing complex (RISC)-loading complex, including Dicer, argonaute-2 (Ago2), and TAR RNA binding protein (TRBP), associated with miRNA, which may be an additional mechanism of RNA loading in exosomes." (PMID 30925917, 2019). "However Ago2 expression and localisation in breast cancer remains undetermined." (PMID 31324173, 2019). "In breast cancer, Cav1 interacts through its scaffolding domain CSD with argonaute-2 (Ago2), a key player in RNA-mediated gene silencing." (PMID 40963741, 2025). "Specifically, the most prevalent kinase fusion genes differed by subtype: MED1::CDK12 in HER2+ breast cancer, PTK2::AGO2 in TNBC, and KAT6B::ADK in HR+/HER2‒ breast cancer." (PMID 41213951, 2025). "A previous study reported that tRF-GlyTCC is a key player in AGO2-independent RNA silencing by sequestering YBX1 and inhibiting YBX1-mediated stabilisation of pro-metastatic mRNAs in breast cancer." (PMID 36936386, 2023). "The results showed that the expression levels of AGO2 and EIF4E3 were significantly lower in breast cancer cell lines than in the normal breast cell line, whereas the expression levels of DCPS and EIF4E were significantly higher." (PMID 37353728, 2023). "To more deeply evaluate the clinical impact of AGO2, EIF4E3 and EIF4E in breast cancer, we used the Kaplan–Meier plotter database to plot the DMFS (distant metastasis-free survival)-related Kaplan–Meier curves of AGO2, EIF4E3 and EIF4E." (PMID 37353728, 2023). "Confirmation of AGO2 expression with miR-17-5p and miR-17-5p-targeted mRNA was performed with hepatocellular carcinoma cell lines HepG2 and JHH-1, breast cancer cell lines MDA-MB-231, prostate cancer cell lines DU145 and PC3, and lung cancer cell line A549." (PMID 35681567, 2022). "It is reported that the exosomes in breast cancer patients’ serum contain RNA-induced silencing-loading complex proteins, TRBP, Dicer, and AGO2, which can process pre-miRNAs into mature miRNAs." (PMID 34829498, 2021). "Another AGO2 PTM, phosphorylation at Y393, was also found to be an adverse prognosis factor, in this case for breast cancer." (PMID 33668654, 2021). "A study was undertaken to assess the effect of 41 SNPs in AGO2 on DFS and OS in 488 Korean breast cancer cases." (PMID 30897768, 2019). "To discern further RISC functions, we analyzed the activities of two RISC proteins, AGO2 and GW182, in the MCF-7 human breast cancer cell line." (PMID 30999843, 2019).
breast carcinoma (continued). "Ectopic expression of miR-145-5p in a panel of breast cancer cell lines (MDA-MB-231, MCF7, SKBR3, MDA-MB-468) induced a consistent increase of Ago2 protein, compared to control miRNA (CTR)." (PMID 30622242, 2019). "AGO2, a key component of miRNA induced gene silencing, is regulated by the EGFR/MAPK signaling cascade and high AGO2 expression levels in ERα− breast cancers have been reported." (PMID 29657266, 2016). "However, several key microRNA processing genes, especially Ago2 and Dicer, were differentially expressed between ER- and ER+ breast cancer, which may explain the different regulatory effects of microRNAs in these two breast cancer subtypes." (PMID 19723326, 2009). "Moreover, we examined the expression levels of genes in the miRNA biogenesis pathway and found that Ago1 and Ago2 (which encode argonautes, the key proteins forming the RNA-induced silencing complex (RISC)) had significantly higher expression levels in ER- than in ER+ breast cancer." (PMID 19723326, 2009). "The combination of YTHDF2 and YAP mRNA reduces the stability of mRNA, while YTHDF2 recruits AGO2 (argonaute RISC catalytic component 2) to promote the degradation of YAP mRNA, affecting the production of related tumor factors and inhibiting the occurrence of tumors in breast cancer." (PMID 41597255, 2026). "Breast cancer cell lines (MDA-MB-231, MDA-MB-468 and SKBR3) and a normal breast cell line (MCF-10A) were used to validate the expression levels of the signature m7GRGs (AGO2, EIF4E3, DCPS and EIF4E)." (PMID 37353728, 2023). "The results showed that the DMFS rates of AGO2 and EIF4E3 were significantly different, which may be related to the metastasis of breast cancer." (PMID 37353728, 2023). "As expected, we found a significant reduction in miR-9 and miR-221 transcripts when AGO2 expression is repressed in the presence of UA treatment compared to the absence of UA in both breast cancer cell lines." (PMID 36613808, 2022). "Breast cancer cell-derived TEX contain the RNA-induced silencing complex (RISC)-loading complex, including argonaute-2 (Ago2), Dicer, and TAR RNA binding protein (TRBP), associated with miRs, which may be an additional mechanism of RNA loading in TEX." (PMID 35163380, 2022). "MiR-542-5p binds to Argonaute 2 (AGO2) and inhibits the expression of DUB3 in breast cancer cells." (PMID 34454495, 2021). "The study did not signal a significant impact of AGO2 SNPs; however, rs595055 C/T, one of the AGO1 genetic variants, was associated with augmented breast cancer risk." (PMID 33668654, 2021). "Interestingly, protein argonaute 2 (AGO2) has been identified to interact with EGFR in serum-starved conditions, and deregulated AGO2 correlates with poor survival in breast cancer patients." (PMID 32138313, 2020). "It has been shown that GAS5 and miR-21 are likely in the same AGO2 complex, and GAS5 could act as a ceRNA to sponge miR-21 in breast cancer cells." (PMID 33203802, 2020). "Clinically, STIM1 and Ago2 expression levels do not correlate with breast cancer progression, however in the basal subtype high STIM1 expression is associated with poorer survival." (PMID 31506588, 2019). "There was an upregulation of AGO2 expression in an estrogen receptor α-negative breast cancer cell line, in prostate cancer as well as in esophageal squamous cell carcinoma tissue, which indicates that AGO2 plays a key role in tumorigenesis." (PMID 29857476, 2018). "AGO2 expression is elevated in colon cancers and oestrogen receptor (ER) alpha-negative breast cancer cell lines." (PMID 24886719, 2014). "We also observed Ago2 in the nuclei of T47D breast cancer cells and fibroblast cells, indicating that nuclear Ago2 is not cell-type specific." (PMID 24388755, 2014). "In addition, the DMFS rates of AGO2 and EIF4E3 were significantly different, which might be related to the metastasis of breast cancer." (PMID 37353728, 2023).